GLO1 (glyoxalase I)
Diseases named in the same sentence as GLO1 in open-access papers (continued):
Sharing a sentence is not in itself a finding about the gene and the disease.
infection (10 papers, 2011 to 2025). The state of being infected such as from the introduction of a foreign agent such as serum, vaccine, antigenic substance or organism. "In parallel, HLA class I antigens and the GLO-1 phenotype of the glyoxalase enzyme have been associated with the progression of disease (pulmonary form) or infection." (PMID 33117339, 2020). "The overexpression of GLO1 in the hippocampus following AAV-GLO1 infection was validated by qRT-PCR." (PMID 40136646, 2025). "Similar to the observations in the case of the antimicrobial genes, the absence of pgp-2 further enhanced K09C4.5, induced glo-3 mRNA levels, and inhibited glo-1 upregulation in response to PA14 infection." (PMID 37704756, 2023). "Using immunofluorescence and Western blot assays, in this study we found for the first time a reduction in Glo1 protein in hearts of Hu-mice seventeen weeks post-infection." (PMID 34970611, 2021). "CD8+ T cells increased in blood of HIV-1 infected Hu-mice and HIV-infected Hu-mice treated with AAV2/9-Endo-Glo1 after 16 weeks of infection." (PMID 34970611, 2021). "Increasing expression of Glo1 in Hu-mice five weeks post-infection using a single dose of an engineered AAV2/9 (1.7 × 1012 virion particles/kg), attenuated the increases in plasma and cardiac MG levels." (PMID 34970611, 2021). "Histopathological and biochemical analyses of cardiac tissues from Hu-mice 17 weeks post-infection affirmed MG increase with a concomitant decrease in expression of the MG-degrading enzyme glyoxalase-1 (Glo1)." (PMID 34970611, 2021). "Indeed, we observed an induction of cyp-35B and gst-4 detoxification genes in response to PA14 infection, which appeared to partially depend on glo-1." (PMID 37704756, 2023). "The requirement of glo-1 and the ABC transporter pgp-2 in the elicitation of the protective responses as well as their role in PA14 infection suggest LRO-associated mechanisms as a novel cellular surveillance program, which helps prepare host defense against various, including pathogen stresses." (PMID 37704756, 2023). "Using this strategy, we show for the first time that increasing expression of Glo1 in hearts of HIV-infected Hu-mice decreased MG and blunted the HF seen 16 weeks post-infection, establishing that elevated MG is an underlying cause of HF in HIV-1-infected Hu-mice." (PMID 34970611, 2021). "In order to assess whether the glyoxalase system was operative in CF, we evaluated the expression and activity of the rate-limiting enzyme GLO1 in the lungs of mice harboring the most common deletion of phenylalanine in position 508 (CftrF508del) after intranasal infection with A. fumigatus conidia." (PMID 34835243, 2021). "A single intravenous injection of AAV2/9-Endo-Glo1 to express the Glo1 five weeks after HIV infection, attenuated impairments in myocardial diastolic and systolic dysfunctions that developed 16 weeks post-infection." (PMID 34970611, 2021). "Representative genes belonging to groups A (SKL2, ECR1), B (UBA1, GLO1 and RPA32) and C (HSC70, ASK2, and deltaCOP) were chosen to evaluate the impact of their silencing on TYLCSV infection, measured as viral DNA accumulation." (PMID 21818318, 2011). "The compensatory expression of several LRO and antimicrobial genes and the prevention of glo-1 and irg-5 induction might explain the detrimental effects of PA14 infection if pgp-2 was lost, suggesting a critical role of PGP-2 in pathogen defense." (PMID 37704756, 2023). "Finally, benzaldehyde preconditioning increases resistance against Pseudomonas aeruginosa PA14 in a glo-1- and pgp-2-dependent manner, and PA14 infection leads to the deposition of fluorescent metabolites in LROs and induction of LRO genes." (PMID 37704756, 2023). "Increasing Glo1 also blunted microvascular leakage, fibrosis, and HF seen at sixteen weeks post-infection, without changes in plasma viral loads." (PMID 34970611, 2021). "GLO1 and RAGE mRNA levels were measured by RT-qPCR after infection with lentiviral shRNA vectors." (PMID 29385725, 2018).
infection (continued). "Interestingly, whereas the loss of glo-1 did not affect the expression of the two other genes, the absence of pgp-2 robustly stimulated irg-1 and induced clec-60 mRNA levels in response to PA14 infection." (PMID 37704756, 2023). "In contrast to the BA-elicited induction of irg-1, glo-1, and pgp-2 were not required for that by PA14 infection, suggesting different LRO-dependent and LRO-independent mechanisms leading to irg-1 upregulation." (PMID 37704756, 2023).
cardiovascular disease (6 papers, 2013 to 2022). "GLO1 CC genotype of (rs4746) polymorphism was associated with significantly higher prevalence of peripheral vascular and cardiovascular diseases in hemodialysis patients." (PMID 29321821, 2017). "In particular, the up-regulation of MIF, CLP36 and GLO1, which are associated with anti-apoptotic, cytoskeleton binding, and detoxifying activities, gives new insights into the understanding of SF pleiotropic behavior in counteracting cardiovascular diseases." (PMID 24349480, 2013). "Finally, a study in human arterial tissues reported significantly lower Glo1 activity in atherosclerotic lesions, compared with normal tissue sections of the same blood vessels, suggesting that the depletion of Glo1 functionality contributes to an increased risk of cardiovascular disease." (PMID 32024152, 2020). "A patient with ESRD and low Glo-1 activity had a high frequency of recurrent cardiovascular disease (CVD) events." (PMID 27406712, 2016).
retinopathy (6 papers, 2015 to 2025). "A polymorphism that alters GLO1 promoter activity has been linked to retinopathy in type 2 diabetic patients." (PMID 33143048, 2020). "Interestingly, a polymorphism that disrupts GLO1 promoter activity has been associated with retinopathy in diabetic subjects." (PMID 34440621, 2021). "We have previously reported that overexpression of GLO-1 in diabetic rats protects against retinopathy." (PMID 25687235, 2015). "In addition, pyridoxamine, an MG scavenger that inhibits AGEs formation but also increases GLO1 activity, prevented the development of retinopathy in streptozotocin-induced diabetic rats." (PMID 33143048, 2020). "Expressions of GLO1 and GLO2 are downregulated in patients with DR, suggesting that dysfunction in this detoxifying system could be behind the development of retinopathy in humans." (PMID 34440621, 2021). "Expression of GLO1 and GLO2 are downregulated in patients with DR, indicating that a failure of this detoxifying system in humans may be involved in retinopathy." (PMID 33143048, 2020).
neurodegenerative disease (5 papers, 2021 to 2025). A disorder of the central nervous system characterized by gradual and progressive loss of neural tissue and neurologic function. "On the other hand, a low GLO1 level may be linked to cell damage and degeneration processes, observed in neurodegenerative diseases." (PMID 40415790, 2025). "Recently, lower GLO1 levels were observed in AD and it was demonstrated that GLO1 is released from neuronal cells through extracellular vesicles (EV), which are known to be involved in neurodegenerative diseases." (PMID 36498925, 2022). "Several studies suggest a role for GLO1 in neurodegenerative disease, such as Alzheimer’s (AD) and Parkinson’s disease (PD) and it has been proposed that dicarbonyl stress may be a hallmark of AD." (PMID 34440621, 2021). "However, several animal models suggest that GLO1 expression is increased in neurodegenerative disease." (PMID 34440621, 2021). "The literature showing the negative effects of MGO during aging and in neurodegenerative diseases also highlighted the potential for protective effects of Glo1 overexpression, which is supported by these studies." (PMID 40867843, 2025).
neurological disorders (5 papers, 2008 to 2023). "Therefore, the presence of the GLO1 A allele appears to play a role in neurological disorders associated with chronic inflammatory processes and AGE formation." (PMID 38027126, 2023). "Regarding the overlapping genes MADD and GLO1 detected in the PWAS and TWAS analyses, previous studies found that they are not only associated with neurological diseases but also have a certain impact on neurological functions." (PMID 35893077, 2022).
psychiatric diseases (5 papers, 2009 to 2025). "Glyoxalase 1 (Glo1) has been implicated in anxiety-like behavior in mice and in multiple psychiatric diseases in humans." (PMID 19266052, 2009). "We have yet to obtain consistent results regarding the relationship between SNVs in GLO1 and psychiatric disorders." (PMID 34953453, 2022). "Thus, rather than discussing the SNVs, it is more important to discuss the relationship between reduced GLO1 activity and psychiatric disorders." (PMID 34953453, 2022). "However, the finding that GLO1 enzymatic activity is decreased in patients with psychiatric disorders is likely to be consistent." (PMID 34953453, 2022). "However, recent years have shown an increased interest in the role of GLO1 and its clinical applications in mental illness." (PMID 34953453, 2022). "According to the present review, the expression and activity of GLO1 in the brain may be involved in the pathogenesis of various psychiatric disorders." (PMID 34953453, 2022). "Multiple lines of evidence suggest a potential role for GLO1 in human psychiatric disorders." (PMID 19266052, 2009). "Furthermore, it has been reported that GLO1 inhibitors may be promising drugs for the treatment of psychiatric disorders." (PMID 34953453, 2022). "However, it is also important to note that recent genome-wide association studies (GWASs) have not shown single nucleotide variants (SNVs) near the GLO1 gene as being relevant to psychiatric diseases." (PMID 34953453, 2022).
metabolic disorders (3 papers, 2020 to 2025). "The role of AGE-independent mechanisms that underly Glo1-induced metabolic disorders have yet to be elucidated." (PMID 39896461, 2025). "AGEs have been implicated as a mediator of Glo1-induced metabolic disorders." (PMID 39896461, 2025). "To explore the role of Glo1 in metabolic disorders, we conducted a systems biology study of Glo1+/− mice." (PMID 39896461, 2025). "Although Glo1 has been previously identified as a candidate gene for human metabolic disorders, the underlying mechanisms have not been explored." (PMID 39896461, 2025). "In the current study, we chose the SHR-Glo1+/− heterozygotes for analysis since GLO1 activity in human metabolic disorders is reduced but not totally suppressed." (PMID 33255888, 2020).
cardiac disease (1 paper, 2022). "The summation of these data show GLO1 dysregulation modulates fatty acid metabolism, and they may provide additional insights into other etiologies of cardiac disease." (PMID 36093169, 2022).
GLO1 also shares sentences with these, for which no sentence is quoted: cognitive decline (3 papers); metastatic melanoma (3); sarcoma (3); complication (2); neuroendocrine tumors (2); Pain (2); renal failure (2); acute myocardial infarction (1); adenoma (1); age (1); amyotrophic lateral sclerosis (1); aspergillosis (1); benign prostatic hyperplasia (1); Bradycardia (1); brain cancer (1); brain ischemia (1); cardiomyopathy (1); cataract (1); cholangiocarcinoma (1); colon adenocarcinoma (1); congenital nonspherocytic hemolytic anemia (1); coronary artery disease (1); ductal carcinoma in situ (1); gestational diabetes mellitus (1); glomerulosclerosis (1); Glucose intolerance (1); heart failure (1); Hernia (1); Hypercholesterolemia (1); hyperhomocysteinemia (1).
A further 20 diseases each share a sentence with GLO1 in 1 paper.